INS (insulin)
Diseases named in the same sentence as INS in open-access papers (continued):
Sharing a sentence is not in itself a finding about the gene and the disease.
Insulin resistance (continued). "Although the higher prevalence of insulin abnormalities and insulin resistance are reported in patients with AD, how AD genetic risk impacts the clinical profiles for diabetic patients, leading to reduced or delayed initialization of insulin therapy determined by their physicians, is unclear." (PMID 34301914, 2021). "These benefits are due to the loss of fat mass, and consequently to the decrease in fasting insulin levels and to the increase in insulin sensitivity, resulting in a decrease of insulin resistance, dyslipidemia, hypertension, and a pro-inflammatory state typical of advanced age." (PMID 34444699, 2021). "However, as seen in mice models in insulin resistance states, high insulin levels have been unable to block transcription factor FOXO1 through AKT2-dependent phosphorylation." (PMID 34943908, 2021). "Regarding circulating parameters, although OW-OB subjects did not present altered glucose levels, they presented signs of insulin resistance, such as increased insulin levels and alterations in insulin resistance parameters: HOMA‐IR, triglyceride-glucose index and QUICKI." (PMID 34526523, 2021). "After 2 months, in the group treated with a new compound (myo-inositol plus α-lactalbumin) a statistically significant reduction of insulin resistance, number of women needed insulin, fetal abdominal circumference value and subcutaneous adipose tissue thickness was demonstrated." (PMID 33893377, 2021). "Second, to dissect the causal relationships more clearly, employing the causal effects of glycemic traits (notably fasting glucose and insulin, the homeostatic model assessment for insulin resistance and beta-cell function, and HbA1c) on the infectious disease would be more helpful." (PMID 34527023, 2021). "Microarrays showed a decrease expression in genes that participate in insulin resistance and in insulin secretion in the PFD group compared to HF group, which indicates that hyperinsulinemia might be caused by a high fat diet." (PMID 34083664, 2021). "Therefore, the inhibition of the PTP-1B expression can ameliorate insulin resistance, leading to an increase in glucose uptake in an insulin-responsive cell, which is considered an important key for a therapeutic target for the treatment of diabetic patients." (PMID 34502417, 2021). "Drugs such as metformin belonging to the class of biguanide inhibit liver glucose production, whilst sulfonylureas and meglitinides that are insulin secretagogues target liver insulin resistance and therefore are utilized to treat IFG or IFG/IGT to improve fasting glycemic responses." (PMID 34835989, 2021). "Of note, htgCB1 mice displayed down-regulation of IDE and its proteolytic activity, but unaltered levels of phosphorylated carcinoembryonic antigen-related cell adhesion molecule 1 (CEACAM1), in parallel with hepatic insulin resistance, lower insulin clearance and moderate hyperinsulinemia." (PMID 33477364, 2021). "Finally, both interventions normalized glucose and insulin content and reversed insulin resistance in SL-TRF1 and SL-TRF2 mice, when compared to their matched controls." (PMID 34684586, 2021). "Additionally, previous studies indicated that sphingolipid ceramide inhibits insulin-stimulated glucose uptake and is one of the main factors involved in the generation of insulin resistance." (PMID 34572415, 2021). "Besides, higher fasting insulin demonstrated hyperinsulinemia in high fat diet fed mice (P <0.05, two-tailed Student’s t-test), further confirming insulin resistance in IR group." (PMID 35116003, 2021). "Although it is known that high fat or sucrose feeding leads to insulin resistance, nobody has ever investigated whether the type of diet triggers different molecules in the insulin signaling pathway." (PMID 33708999, 2021).
Insulin resistance (continued). "The top 10 DPN-related metabolic pathways, obtained by KEGG enrichment analysis of intersection targets, included insulin resistance, type II diabetes, and insulin signaling pathways, indicating that one of the main mechanisms of SL in the treatment of DPN is the regulation of blood glucose." (PMID 34306139, 2021). "Insulin resistance is one of the variables in metabolic syndrome associated with MAFLD and it is defined as a decrease or an insufficient insulin sensitivity in the target tissues, such as in muscle, adipose tissue, and liver towards glucose uptake from the blood." (PMID 34822647, 2021). "In the current study, we found that caveolin-1 could play a vital role in alleviating insulin resistance during insulin treatment by activating AKT phosphorylation." (PMID 34917687, 2021). "Indeed, many studies have confirmed the association between high levels of LPS or proinflammatory markers and inhibition of insulin pathways on target organs, justifying the found insulin resistance." (PMID 33668627, 2021). "We next investigated whether GLP-1R agonists and L-dopa had an effect on the fasting plasma level of insulin, glucose, and the insulin resistance index (HOMA-IR) values." (PMID 34830228, 2021). "Whether the effect of aldosterone, many times inappropriately secreted in SS subjects, plays a role in determining insulin resistance via hybridization of the insulin and insulin growth factor receptors is not known." (PMID 34966295, 2021). "Likewise, there was a shift in the insulin secretory pattern, improvement in insulin resistance, and a profound lowering of leptin levels." (PMID 34950778, 2021). "In addition, the prebiotic groups displayed lower leptin levels, fasting glucose, fasting insulin and insulin resistance compared to the ABT group." (PMID 33445530, 2021). "In addition, both HIIT and CRT also had positive effects on insulin resistance, insulin, and LDL levels." (PMID 35197860, 2021). "Insulin resistance is an altered response of insulin receptors to a given insulin concentration." (PMID 34069890, 2021). "Besides, the increased expression of ANGPTL8 in insulin resistance model or T2DM suggests that insulin signalling also plays a regulatory role in ANGPTL8." (PMID 34582711, 2021). "The variation might be attributed to the majority of participants in this were diabetics with complication in which, patients who have insulin resistance with decrease in excretion of UA due to the reduced effects of insulin action." (PMID 34506522, 2021). "Increased insulin resistance in patients with T1D (receiving insulin) could be determined directly by using only an insulin clamp, but clinically it is indirectly measured by a parameter of a daily dose of insulin per kilogram." (PMID 34608175, 2021). "In T2D, the increased insulin production due to insulin-resistance, could led to an increase of miR-15 synthesis." (PMID 34638838, 2021). "This acidification causes insulin resistance via reduction of insulin affinity to its receptor, resulting in a larger increase in HbA1c due to elevation of PBS compared with elevation of insulin-independently controlled FBS from the age of 60s to 70≦." (PMID 34681771, 2021). "In addition, it has been proven that TNFα induces insulin resistance by interfering with insulin signaling directly and indirectly." (PMID 34068151, 2021). "Further functional studies showed that the loss of specificity of CBLB led to insulin and glucose tolerance test response disorder, and blocking CBLB-induced macrophage activation could improve insulin resistance." (PMID 35046894, 2021). "One of the possible reasons for this phenomenon is that hyperuricemia could promote insulin secretion to compensate for insulin resistance in the short term." (PMID 33520463, 2021).
Insulin resistance (continued). "Although the studies reviewed do not all show a consistent pattern of regulation of BCAA catabolism enzymes in muscle, they all point to altered tissue and whole-body metabolism of these AAs in obesity/insulin resistant states, and that correcting such defects ameliorates insulin resistance." (PMID 34354601, 2021). "Data were not collected from muscle or adipose tissues which are peripheral tissues that may have contributed to insulin resistance and the pancreas, which are sources of insulin secretion." (PMID 33972568, 2021). "Mice with liver-specific overexpression of follistatin exhibited increased hepatic glucose production, as well as aggravated insulin resistance in adipose tissue and skeletal muscle accompanying whole-body glucose intolerance, while follistatin knockdown improved insulin sensitivity." (PMID 34944728, 2021). "Moreover, the first axis (PC1) was mainly characterized by the group of variables related to insulin resistance (fasting glucose, fasting insulin, fasting TG, TyG index, and HOMA-IR)." (PMID 33804501, 2021). "But diets containing saturated fat, not only promote hepatic triglyceride accumulation, but also favor gluconeogenesis, resulting from allosteric activation of pyruvate carboxylase flux and increased glycerol flux, and induce insulin resistance by lipid-mediated inhibition of insulin signaling." (PMID 33839905, 2021). "As, galanin deficiency might at least be one of the efficient factors associated with insulin resistance in PCOS, it is hypothesised that the administration of galanin can increase insulin sensitivity." (PMID 33740336, 2021). "hydroalcoholic extract decreased blood glucose, insulin resistance, leptin and IL-6 levels, lipid profile, and vascular dysfunction, while increasing the expression of insulin signaling proteins in skeletal muscle, adipose tissue and plasma glucagon like peptide-1 (GLP-1) levels." (PMID 33435282, 2021). "Children who were born VP/VLBW had significantly lower fat masses, higher systolic BP and diastolic BP, and significantly higher values of fasting glucose, insulin, and homeostatic model assessment of insulin resistance (HOMA-IR), compared to children born at term." (PMID 34465300, 2021). "Nonetheless, our results from the POEM study are consistent with the idea that FFA are a major candidate driving fasting insulin secretion and fasting hyperinsulinemia, which may initiate insulin resistance, especially in the liver." (PMID 33712379, 2021). "In addition, due to the systemic insulin resistance, the high levels of insulin will contribute to DNL." (PMID 34526911, 2021). "Thus, an acute bout of exercise instantly helps to remove glucose and lipids from the circulation and can mitigate insulin resistance by enhancing insulin-stimulated glucose uptake for up to two days after exercise cessation." (PMID 33801684, 2021). "When evaluated in the setting of obesity-related insulin resistance, high doses of insulin may be pro-inflammatory." (PMID 33992101, 2021). "Apart from being a marker for cellular stress and hypoxia, LDH may induce insulin resistance and inhibits insulin action." (PMID 34071554, 2021). "This is happen due to the insensitivity of insulin from the insulin resistance that may reduce the production of insulin and finally leading to excessive blood glucose level or known as hyperglycaemia." (PMID 33249946, 2021). "Insulin resistance (IR) refers to insensitivity to insulin-mediated glucose disposal." (PMID 33907673, 2021). "Similarly, EVs from AT macrophages of obese mice induced insulin resistance, whereas those from lean mice increased insulin sensitivity in obese mice." (PMID 33539327, 2021). "Based on the results of the changes in insulin sensitivity and islet β-cell secretion function in our study, we found that KS patients with hyperglycemia presented with similar insulin resistance levels but better islet β-cell secretion function than those without KS." (PMID 34852815, 2021).
Insulin resistance (continued). "In a randomized, placebo-controlled crossover study in overweight and obese subjects—the Healthy Aging Through Functional Food (HATFF) study—treatment with tRES-HESP reversed insulin resistance, with an improvement of insulin sensitivity in obese subjects comparable to outcomes of metabolic surgery." (PMID 34371884, 2021). "The discovery of new effectors of the insulin signaling pathway could provide novel therapeutic approaches for the treatment of insulin resistance and T2D." (PMID 33647317, 2021). "The cell population(s) in the DVC that are involved in insulin sensing and insulin resistance remain unknown." (PMID 33227495, 2021). "TNFα disrupts the insulin signaling pathway by disrupting such phosphorylation events, specifically by inhibiting the phosphorylation of IR substrate 1, leading to a subsequent decreased glucose uptake, and eventual insulin resistance." (PMID 34576943, 2021). "Additionally, patients with persistent hepatocyte ballooning after metabolic surgery exhibited insulin resistance, while the patients who exhibited elimination of hepatocyte ballooning after the surgery demonstrated improved insulin resistance." (PMID 34321567, 2021). "It has been clearly documented by human and animal studies that both acute exercise and physical training are capable to ameliorate the molecular abnormalities that are responsible of the insulin resistance, contributing in this way to restore the physiological insulin sensitivity." (PMID 32737757, 2021). "In contrast with ER-/PR- patients, a negative association is noted between insulin resistance and tumor recurrence in ER+/PR+ people, which is consistent with serum insulin levels." (PMID 33842335, 2021). "However, Mem significantly decreased blood insulin levels and improved glucose tolerance and insulin resistance induced by HFD." (PMID 33500723, 2021). "Stimulants that evoke insulin secretion even at low level may contribute to inducing peripheral insulin resistance." (PMID 34072220, 2021). "It is possible that too much alcohol consumed post-exercise could negatively impact blood glucose via acute insulin resistance, and a direct relationship between reduced muscle mass and insulin-stimulated skeletal muscle GLUT-4 activation." (PMID 34069950, 2021). "The use of medications reducing insulin resistance such as metformin may be beneficial in T2DM patients receiving insulin treatment." (PMID 33598483, 2021). "Upon being released in the bloodstream by visceral fat, adiponectin promotes fatty acid oxidation and protects against insulin resistance, since it decreases glucose and insulin levels by increasing tissues insulin sensitivity and glucose uptake in feeding conditions." (PMID 34205356, 2021). "In conclusion, growing Iberian pigs challenged with an IAGTT showed changes in biochemical parameters and insulin response that may indicate an early stage of insulin resistance." (PMID 33854837, 2021). "Indeed, adipokines contribute to peripheral insulin resistance and disorders of lipid metabolism mainly interfering with insulin signaling pathways." (PMID 34439477, 2021). "The term insulin resistance is very wide and could affect different proteins involved in insulin signaling, as well as other mechanisms." (PMID 34069890, 2021). "Insulin sensitivity has been shown to be impaired in patients with migraine, and additionally, abdominal obesity is a significant risk factor for insulin resistance in women with and without migraine." (PMID 33855218, 2021). "In fact, VLDL-TG secretion is less sensitive to insulin inhibition in NAFLD subjects (hepatic insulin resistance), implying that the secretion of larger VLDL particles remains unabated during feeding cycles, thus contributing to dyslipidemia observed in NAFLD subjects." (PMID 33669443, 2021). "Emerging investigations have indicated that SGLT2 inhibitors might influence insulin signal transduction, improve peripheral insulin sensitivity, and thus alleviate insulin resistance." (PMID 34439414, 2021).
Insulin resistance (continued). "These negative genetic correlations corroborate the epidemiological associations, previous research findings and clinical observations of CRF and PA and body composition, lipid profile, adipocytokines, fasting insulin and insulin resistance and leptin, T2D and CAD." (PMID 34753499, 2021). "Insulin resistance represents a reduced ability of tissues to respond to insulin action." (PMID 33584134, 2021). "Thus, PM2.5-induced inflammation activation and insulin signaling inhibition in the rat liver contribute to the development of systemic insulin resistance." (PMID 34745386, 2021). "Indeed, eating fast can induce insulin resistance by the chronic elevations of plasma insulin levels." (PMID 33419065, 2021). "Furthermore, TNF-α and IL-6 concentrations are generally related to insulin levels; in fact, these cytokines play an important role in the pathogenesis of insulin resistance." (PMID 33530512, 2021). "While type 2 diabetes is caused by insulin resistance, in which insulin is secreted properly but the cells do not respond appropriately, type 1 diabetes is more associated with abnormal insulin production." (PMID 34836306, 2021). "In addition, HOMA, which is a method for assessing β-cell function and insulin resistance (IR) from basal (fasting) glucose and insulin or C-peptide concentrations were also significantly higher in the DCAN group compared with control." (PMID 34795728, 2021). "To further explore the underlying mechanism of how COX-2 protects the liver from HF diet-induced liver steatosis and insulin resistance, we investigated several critical nutritional components of liver metabolism, along with the main regulatory pathway of insulin-AKT response." (PMID 33662521, 2021). "Likewise, green tea polyphenols attenuated the insulin resistance by stimulating the insulin signaling in the soleus muscle and improved the metabolic status in obese Zucker rats." (PMID 34208379, 2021). "Overproduction of pro-inflammatory cytokines (including TNF- and IL-6) in adipose tissue, as well as an imbalance between adipokines that increase or reduce tissue sensitivity to insulin (adiponectin and resistin), are typical of insulin resistance disturbances." (PMID 34299201, 2021). "Additionally, HC was shown to increase the sensitivity of insulin in palmitate-induced insulin resistance 3T3-L1 adipocytes, as reflected by stimulating glucose uptake and reducing lipolysis." (PMID 34394985, 2021). "Insulin resistance was intensified by ADP for further impairment in insulin tolerance." (PMID 33986729, 2021). "BCAAs are positively correlated with insulin resistance and T2DM; this could be a compensatory homeostatic reaction to deal with insulin resistance by stimulating insulin production." (PMID 34830706, 2021). "Therefore, exploring the potential regulatory mechanism of insulin signaling is helpful to better understand the pathogenesis of systemic insulin resistance." (PMID 34373742, 2021). "Indeed, mice with global null mutation or with liver-specific inactivation of Ceacam1 gene display hyperinsulinemia due to their impaired insulin clearance, which in turn induces insulin resistance in these mice." (PMID 34054736, 2021). "In the short term, hyperinsulinemia can compensate for insulin resistance and allow maintenance of normoglycemia, but insulin sensitivity is heterogeneous between tissues, so some insulin-sensitive tissues may exhibit elevated insulin-mediated activity." (PMID 33806509, 2021). "Vascular dysfunction could also be related to insulin resistance, and our results suggest that insulin signaling could be impaired in diabetic rats in both sexes." (PMID 34366875, 2021). "Moreover, MaR1 improves insulin resistance (IR) and lipid disorders by stimulating insulin signalling." (PMID 34461919, 2021).